ENSG00000301546 (novel transcript, antisense to UBC)
Gene: Long non-coding RNA gene on chromosome 12 (124,915,318 to 124,921,893, forward strand). Ensembl gene ENSG00000301546.
Gene Ontology:
Molecular function: triplet codon-amino acid adaptor activity
Biological process: translation